NDUFA8 (NADH:ubiquinone oxidoreductase subunit A8)
Description:
Accessory subunit of the mitochondrial membrane respiratory chain NADH dehydrogenase (Complex I), that is believed not to be involved in catalysis. Complex I functions in the transfer of electrons from NADH to the respiratory chain. The immediate electron acceptor for the enzyme is believed to be ubiquinone.
Synonyms: CI-19kD; CI-PGIV; PGIV; MGC793; MC1DN37
Tractability: Small molecule: an approved drug acts on it; a structure with a bound ligand is known. Antibody: UniProt places it where antibodies can reach, with high confidence. PROTAC: ubiquitination databases record sites on it; its protein half-life has been measured.
Gene: Protein-coding gene on chromosome 9 (122,144,058 to 122,159,779, reverse strand). Ensembl gene ENSG00000119421.
Subcellular location: Mitochondrion inner membrane; Mitochondrion intermembrane space; Mitochondrion
Subcellular location (Human Protein Atlas): Mitochondria; End piece; Mid piece; Principal piece
Pathways (Reactome):
Metabolism: Complex I biogenesis; Respiratory electron transport
Gene Ontology:
Molecular function: protein binding; protein-containing complex binding; NADH dehydrogenase (ubiquinone) activity
Biological process: aerobic respiration; mitochondrial electron transport, NADH to ubiquinone; proton motive force-driven mitochondrial ATP synthesis; proton transmembrane transport
Cellular component: mitochondrial inner membrane; mitochondrial intermembrane space; mitochondrion; respiratory chain complex I
Genetic constraint (gnomAD): Loss-of-function variants: 13 observed, 18.66 expected, observed/expected ratio (o/e) 0.7, 90% interval 0.45 to 1.11. The upper end of that interval is the gene's LOEUF score, 1.11, which puts it in group 4 of 6, group 1 being the genes least tolerant of losing a copy. Missense variants: 161 observed, 187.95 expected, observed/expected ratio (o/e) 0.86, 90% interval 0.75 to 0.98. Synonymous variants: 61 observed, 67.74 expected, observed/expected ratio (o/e) 0.9, 90% interval 0.73 to 1.11.
Gene-disease validity (ClinGen):
ClinGen rates the evidence that NDUFA8 causes each of these diseases.
mitochondrial disease (autosomal recessive): Moderate.
Homologues: Orthologues: chimpanzee NDUFA8 (100% identical), macaque NDUFA8 (95% identical), guinea pig NDUFA8 (91% identical), pig NDUFA8 (91% identical), rat Ndufa8 (90% identical), dog NDUFA8 (88% identical), mouse Ndufa8 (87% identical), rabbit NDUFA8 (83% identical), tropical clawed frog ndufa8 (74% identical), zebrafish ndufa8 (74% identical), Drosophila melanogaster ND-19 (44% identical), Caenorhabditis elegans ndua-8 (28% identical).
Diseases named in the same sentence as NDUFA8 in open-access papers:
NDUFA8 is named in the same sentence as 28 diseases in open-access papers, as found by Europe PMC text mining. Sharing a sentence is not in itself a finding about the gene and the disease. The quoted sentences say what the papers report.
Huntington disease (2 papers, 2012 to 2018). Huntington disease (HD) is a rare neurodegenerative disorder of the central nervous system characterized by unwanted choreatic movements, behavioral and psychiatric disturbances and dementia. "For example: Huntington’s disease (NDUFA7, NDUFC1, NDUFB2, NDUFB3, NDUFA8), atrophy of optic nerve (NDUFS4) and Leigh syndrome (NDUFS7, NDUFA2, NDUFS4)." (PMID 23028713, 2012).
Parkinson disease (2 papers, 2018). A progressive degenerative disorder of the central nervous system characterized by loss of dopamine producing neurons in the substantia nigra and the presence of Lewy bodies in the substantia nigra and locus coeruleus. "Next we interrogated the KEGG pathway and found the top up-regulated categories showed strong correlation with Alzheimer’s, Huntington’s and Parkinson’s diseases by enriching genes such as ATP5D, ATP5H, HSD17B10 and NDUFB11, NDUFA8, NDUFB7, NDUFS8." (PMID 29915338, 2018).
developmental delay (1 paper, 2022). "Homozygous variants in NDUFA8 are associated with developmental delay, microcephaly and epilepsy due to deficiency of mitochondrial complex I. NDUFA8 deletion results in severe defects in mitochondrial complex I assembly, resulting in progressive neurological and developmental abnormalities." (PMID 36361522, 2022).
melanoma (1 paper, 2019). A malignant, usually aggressive tumor composed of atypical, neoplastic melanocytes. "To further substantiate the therapeutic potential of targeting mitochondrial CI, we constructed a stable NDUFA8 knockdown in the H1 melanoma cell line (H1_shNDUFA8)." (PMID 30971321, 2019).
Non-alcoholic fatty liver disease (1 paper, 2017). "NDUFA8 (Cluster 5), NDUFS6, and GSK3B (Cluster 2) were mapped to “Non-alcoholic fatty liver disease (NAFLD)”." (PMID 28445522, 2017).
infection (1 paper, 2023). The state of being infected such as from the introduction of a foreign agent such as serum, vaccine, antigenic substance or organism. "Full complementation was observed for the expression levels of TRIM39, SARM1, SLC25A26, NDUFA8 and DTYMK by infection with C∆tbcm, which showed similar trends as wild-type BCG infection." (PMID 38110948, 2023).
mitochondrial disease (1 paper, 2023). "Furthermore, compared to the wild-type BCG group, the transcriptome of the B∆tbcm group showed downregulated genes, including SLC25A26 (− 3.276-fold), NDUFA8 (− 3.324-fold) and DTYMK (− 2.931-fold); the absence of these genes is associated with mitochondrial disease." (PMID 38110948, 2023).
NDUFA8 also shares sentences with these, for which no sentence is quoted: cervical cancer (5 papers); bladder cancer (3); colorectal cancer (3); esophageal cancer (2); esophageal squamous cell carcinoma (2); prostate carcinoma (2); Alzheimer disease (1); angiomyolipoma (1); brain diseases (1); cancer (1); cardiomyopathy (1); chronic myelogenous leukemia (1); epilepsy (1); kidney (1); lactic acidosis (1); Leigh syndrome (1); microcephaly (1); neurodegenerative disease (1); neurological diseases (1); non-small cell lung carcinoma (1); tumor (1).